MIR137 (microRNA 137)
Synonyms: hsa-mir-137; miR-137; MIRN137
Gene: MicroRNA gene on chromosome 1 (98,046,070 to 98,046,171, reverse strand). Ensembl gene ENSG00000284202.
Gene Ontology:
Biological process: miRNA-mediated post-transcriptional gene silencing
Cellular component: RISC complex
Homologues: Orthologues: chimpanzee ptr-mir-137 (100% identical), macaque mml-mir-137 (100% identical), pig MIR137 (100% identical), rabbit MIR137 (100% identical), rat Mir137 (97% identical), tropical clawed frog xtr-mir-137-1 (90% identical), zebrafish dre-mir-137-2 (83% identical), zebrafish dre-mir-137-1 (77% identical), mouse Mir137 (72% identical), Drosophila melanogaster mir-137 (54% identical).
Diseases named in the same sentence as MIR137 in open-access papers:
MIR137 is named in the same sentence as 16 diseases in open-access papers, as found by Europe PMC text mining. Sharing a sentence is not in itself a finding about the gene and the disease. The quoted sentences say what the papers report.
schizophrenia (18 papers, 2011 to 2025). A major psychotic disorder characterized by abnormalities in the perception or expression of reality. "We show that MIR137, one of the strongest GWAS loci associated with schizophrenia and intellectual disability, is expressed specifically in Cajal-Retzius cells, an early-born but transient population that guides subsequent cortical neuron migration." (PMID 40964041, 2025). "MIR137 is also one of the strongest GWAS-associated loci for schizophrenia and intellectual disability, with established roles in synaptic development and epigenetic regulation." (PMID 40964041, 2025). "In conclusion, to our knowledge, this study is the first to show that MIR137 SNPs are significantly associated with schizophrenia in the Han Chinese population." (PMID 33708240, 2021). "Genome-wide association studies (GWAS) have suggested that rs1625579 of MIR137 was the strongest locus associated with schizophrenia." (PMID 33708240, 2021). "Analysis of the MIR137 haplotype rs1198588-rs2660304 showed a significant association with schizophrenia in haplotype T-T [χ2 = 4.60, p = 0.032, OR = 1.32, 95% CI (1.02–1.70)]." (PMID 33708240, 2021). "In the present publication, we analyzed the association of MIR137 rs1625579 gene polymorphism with susceptibility to schizophrenia in Belarusian population, as well as its relationship with symptom severity and cognitive functioning." (PMID 30026708, 2018). "As rs1625579 (a risk factor for schizophrenia), is in linkage disequilibrium with rs2660304, a possible functional role of rs1625579 as a factor regulating MIR137 expression by means of rs2660304 polymorphism was suggested." (PMID 30026708, 2018). "Significant association of MIR137 rs1625579 polymorphism with symptom expression degree according to PANSS in schizophrenia patients." (PMID 30026708, 2018). "In summary, the data obtained indicate that rs1625579 polymorphism of MIR137 gene is associated with symptom severity in patients with schizophrenia; furthermore, sex-dependent differences of this association were revealed." (PMID 30026708, 2018). "Currently, the studies of MIR137 rs1625579 association with susceptibility to schizophrenia hold the leading position, nevertheless the number of data points to the contradictory results for different ethnic groups." (PMID 30026708, 2018). "We demonstrated that EU358092 was as conserved as MIR137 and that the mRNA was tagged by many SNPs significantly associated with schizophrenia by GWAS over the locus." (PMID 27913161, 2017). "A microRNA, MIR137, within this locus has been proposed as the gene causally associated with schizophrenia, due to its known role as a regulator of neuronal development and function." (PMID 27913161, 2017). "As the MIR137 locus is shown to be highly associated with schizophrenia through GWAS, new ESTs and RNAs from within this region warrant further study for their potential involvement in brain development and function." (PMID 27525637, 2016). "In our study, we identified seven non-coding ECRs with potential transcriptional regulatory function at the schizophrenia-associated MIR137 locus." (PMID 27525637, 2016). "MIR137 has been identified as a candidate gene for schizophrenia from genome-wide association studies via association with an intronic single nucleotide polymorphism (SNP), rs1625579." (PMID 25154622, 2015). "Interestingly, genome-wide association and proteomic studies have implicated the MIR137 host gene, and the mRNA targets of miR-137 are risk genes for schizophrenia." (PMID 40667070, 2025). "At present, the biological mechanisms of MIR137 rs1198588 and rs2660304 polymorphisms are still unclear, but the results of our case-control study provide convincing evidence for the association between MIR137 polymorphisms and schizophrenia." (PMID 33708240, 2021).
schizophrenia (continued). "Increasing evidence has shown that MIR137 and its gene regulatory network may be involved in the genetic and biological basis of schizophrenia and have been associated with phenotypes in schizophrenia, such as age of onset and brain structure and function." (PMID 33708240, 2021). "Among them, MIR137, a micro-RNA, which is a regulator of neuronal development, showed the strongest association in schizophrenia (p-value = 1.6 × 10−11), and three more loci (CACNA1C, ANK3, and ITIH3-ITIH4) were significantly associated with both BD and schizophrenia." (PMID 34502224, 2021). "Association studies of MIR137 rs1625579 polymorphism with risk of schizophrenia." (PMID 30026708, 2018). "The Genome-Wide Association Studies (GWAS) have shown that MIR137 gene may be considered as a strong candidate to be included to the existing list of 108 gene loci of schizophrenia susceptability." (PMID 30026708, 2018). "These targets have been postulated to include transcripts from many schizophrenia associated genes, such as CACNA1C, and thus MIR137 has been highlighted as a potential modulator of CNS function that could reveal underlying schizophrenia biology." (PMID 27913161, 2017). "Therefore, MIR137 associated risk for schizophrenia may be implicated with its downstream genetic effects." (PMID 29118371, 2017). "Overall, MIR137 appears to be an integral part of the biological pathways of schizophrenia and a component of the genetic architecture of the complex phenotypes of schizophrenia." (PMID 33708240, 2021). "Transcriptional targets of MIR137, such as ZNF804A and CACNA1C, as well as the gene itself, have been implicated with schizophrenia." (PMID 31078131, 2019). "Based on the data with sex differences in the locus rs1625579, it is possible to assume that MIR137 gene is involved in pathophysiological mechanisms leading to gender phenotypically distinct patterns of schizophrenia." (PMID 30026708, 2018). "The product of MIR137 gene, microRNA-137 (miR-137), may be involved in pathophysiology of schizophrenia by affecting synaptogenesis, neurogenesis in adults, synaptic plasticity as well as many other aspects of the central nervous system development." (PMID 30026708, 2018). "Another neurological disorder Schizophrenia has also been tested upon using CRISPR/Cas9, using a mouse model a single intracranial injection of AAV2g9 vectors encoding guide RNAs targeting the schizophrenia risk gene MIR137 (encoding MIR137) was used." (PMID 29592810, 2018). "Regarding MIR137, SNP rs1625579 has been previously associated with smaller hippocampal volumes in patients with schizophrenia, but we did not observe this effect in our sample of healthy controls." (PMID 25217366, 2014). "Using the PGC2 secondary analysis schizophrenia case-control cohort (N = 29,125 cases and 34,836 controls), a robust polygenic signal was observed from gene sets based on TCF4, FMR1, upregulation from MIR137 and downregulation from CHD8." (PMID 31078131, 2019).
autism (1 paper, 2019). Persistent deficits in social interaction and communication and interaction as well as a markedly restricted repertoire of activity and interest as well as repetitive patterns of behavior. "We previously found that mice with one copy of Mir137 disrupted in the brain display autism-like behavior, dendritic and synaptic overgrowth, and impaired learning and social behavior." (PMID 31736707, 2019).
colorectal cancer (1 paper, 2023). A primary or metastatic malignant neoplasm that affects the colon or rectum. "Therefore, HSF1 regulated DNMT3a/MIR137HG/MIR137 / GLS axis to raise glutaminolysis and mTOR activation and promote the process of colorectal cancer, and it is a potential therapeutic target for colorectal cancer." (PMID 37127605, 2023).
gastric cancer (1 paper, 2022). A primary or metastatic malignant neoplasm involving the stomach. "The purpose of the article: The MIR137 gene acts as a tumor-suppressor gene in colon and gastric cancers." (PMID 35996520, 2022).
Hypoglycemia (1 paper, 2025). A decreased concentration of glucose in the blood. "Mir137−/− showed significant hypoglycemia under starvation condition and hypothermia compared with Mir137+/+." (PMID 40598150, 2025). "Moreover, in the context of hypoglycemia observed in Mir137−/−, the expression level of Slc2a4 (Glut4), a glucose transporter involved in carbohydrate metabolism and modulated by GH/GHR signaling, was also reduced." (PMID 40598150, 2025).
lung carcinoma (1 paper, 2026). "Seven tumor suppressor genes (CDKN2A, CDH13, MGMT, MIR137, DAPK1, RARB, and RASSF1A) consistently exhibited hypermethylation in both lung cancer and in association with smoking exposure." (PMID 42073597, 2026).
neuroblastoma (1 paper, 2017). Neuroblastoma (NB) is the most common solid, extracranial childhood tumor. "Stimulus inducible expression of EU358092 in response to drug challenge was demonstrated in vitro in SH-SY5Y neuroblastoma cells, which was again similar to previous expression patterns observed for MIR137, consistent with both RNAs responding to related transcriptional cues." (PMID 27913161, 2017).
Osteopenia (1 paper, 2025). Osteopenia is a term to define bone density that is not normal but also not as low as osteoporosis. "In bone formation, H&E staining showed Mir137−/− had osteopenia with loss of bone mass at the distal femur condyle compared with Mir137+/+." (PMID 40598150, 2025).
neurodevelopmental disorder (1 paper, 2025). A behavioral and cognitive disorder with onset during the developmental period that involves impaired or aberrant development of intellectual, motor, or social functions. "Because MIR137 regulates genes involved in chromatin remodeling, synaptic function, and neuronal maturation, its misexpression during the narrow developmental window when CR cells are active may contribute to neurodevelopmental disorders." (PMID 40964041, 2025).
MIR137 also shares sentences with these, for which no sentence is quoted: bipolar disorder (1 paper); Intellectual disability (1); nasopharyngeal carcinoma (1); neurological disorder (1); psychiatric disorder (1); psychosis (1); tumor (1).